BCL2 (BCL2 apoptosis regulator)
Diseases named in the same sentence as BCL2 in open-access papers (continued):
Sharing a sentence is not in itself a finding about the gene and the disease.
thyroid cancer (continued). "Furthermore it was shown in different studies that BCL-2 expression is strong in most differentiated thyroid carcinoma but decreases in less differentiated subtypes." (PMID 27042160, 2016). "The low IC50 values for GX15-070 that we observed in most of our thyroid carcinoma cells hint at so far unknown cellular target proteins that have a higher affinity to GX15-070 than BCL-2 proteins." (PMID 26198850, 2015). "We have shown that in thyroid cancer cells sorafenib induces apoptosis by affecting Mcl-1 and Bcl-2 in BRAFV600E mutated cells which was independent of BRAF." (PMID 19878585, 2009). "Klhl14AS has already been described as ceRNA in thyroid cancer, where it acts as a decoy for miRNA182-5p and miRNA20a-5p, reducing their binding to the transcripts of both Pax8, a master regulator of thyroid differentiation, and Bcl2, a survival-promoting gene essential in thyroid physiology." (PMID 37238229, 2023). "The present data also reveal that the determination of Bax, Bcl-2, IL-8 and TNF-α levels might possess a potential prognostic and diagnostic value in thyroid cancer patients, reflecting that apoptosis and inflammation are important mechanisms in thyroid cancer." (PMID 35203561, 2022). "Although thyroid cancer cells remain to be explored in combination with typical Bcl-2 inhibitor and Gal-3 inhibitor, targeting Gal-3 might be effective to improve the efficacy of Bcl-2 targeted therapy." (PMID 25393982, 2014). "Cd-induced thyroid cancer rats exhibited alterations in the level of mRNA expression viz., ERK4, Bax, Bcl-2, ERK1, MEK1, elf2α, p-elf2α, GRP78, GRP94 and Lusianthridin treatment significantly (P < 0.001) restored the level of mRNA expression." (PMID 38449627, 2024). "Auranofin induced apoptosis in thyroid cancer cells through the upregulation of BAX and cleaved PARP and downregulation of Bcl-2." (PMID 39459033, 2024). "Abemaciclib lowered mRNA levels of the anti-apoptotic gene Bcl-2 in SW1736 and C643 thyroid carcinoma cells." (PMID 38170401, 2024). "Our data also showed that KA kills thyroid cancer cells by inhibiting the MAPK/ERK pathway and decreasing Bcl-2 level." (PMID 34264510, 2022). "TBX15 acts as an anti-apoptotic factor in thyroid cancer by inhibiting the expression of proapoptotic BAX and increasing the expression of antiapoptotic BCL2 and BCL-XL regulators." (PMID 33447348, 2020). "Silencing of TCTN1 was suggested to induce human thyroid cancer cell apoptosis through over-expression of cleaved caspase-3 and PARP and repression of Bcl-2." (PMID 31297133, 2019). "BCL2 inhibitors synergize with MEK inhibitors and induce in vitro death of murine poorly differentiated thyroid carcinoma cells." (PMID 26636651, 2015). "With respect to the histological origin, there again was no obvious correlation of expression of the anti-apoptotic proteins BCL-2, BCL-xL and MCL-1 with thyroid carcinoma subtype of cell lines." (PMID 26198850, 2015). "Our results are consistent with a previous study using thyroid cancer cell lines; SAHA down-regulated expression of anti-apoptotic genes, including Bcl-2 and survivin, and cleavage of PARP." (PMID 20846458, 2010). "We also confirmed that KA induced apoptosis of thyroid cancer cells is mainly related to Bcl-2 signaling pathway, but not related to caspase-3." (PMID 34264510, 2022). "Furthermore, the determination of Bax, Bcl-2, IL-8 and TNF-α levels constitute a major important marker for investigation of the mechanisms of apoptosis and inflammation in thyroid cancer." (PMID 35203561, 2022). "In previous studies, chrysin could increase Bax and decrease Bcl-2 in hepatocarcinoma cells, whereas c-PARP levels increased in thyroid cancer cells." (PMID 36555388, 2022).
thyroid cancer (continued). "Although the specific biological functions of BCL2 and LPAR5 genes in PTC had not been explored directly by molecular biology methods, data mining based on bioinformatics tools had also confirmed that BCL2 gene was down-regulated in PTC, and LPAR5 gene was up-regulated in thyroid cancer." (PMID 30872410, 2019). "Based on the importance of BCL-2 proteins for uncontrolled proliferation and therapy resistance of malignant tumor cells, we studied the effect of the BH3 mimetic GX15-070 on a panel of 17 thyroid carcinoma cell lines." (PMID 26198850, 2015). "In addition, sesquiterpene lactones, such as alantolactone and isoalantolactone, from Inula helenium have been reported to induce intrinsic apoptosis in thyroid cancer and oral squamous carcinoma cells through ROS generation, BAX/BCL-2 ratio modulation, and caspase-3 activation." (PMID 40864793, 2025). "Based on the importance of BCL-2 proteins for apoptosis and for the therapy resistance of cancer cells, we studied the effect of the BH3 mimetic ABT-737 on proliferation and cell death induction in different thyroid carcinoma cell lines alone and in combination with chemotherapeutic drugs." (PMID 27042160, 2016). "Induction of autophagy by ABT-737 by disrupting the interaction of BECLIN1 with BCL-2 and BCL-xL was also indicated in single reports but was not seen in our thyroid carcinoma cells as no LC3B cleavage following ABT-737 incubation was depicted." (PMID 27042160, 2016).
breast tumor (63 papers, 1996 to 2025). "Expression of BCL2, an antiapoptotic protein, is associated with low-grade, slowly proliferating, ER+ breast tumours." (PMID 20664598, 2010). "The purpose of the present study was to examine expression patterns of Bag-1 in a large cohort of breast tumors and to assess the association with Bcl-2, estrogen receptor, progesterone receptor and Her2/neu, and other clinical/pathological variables." (PMID 18430249, 2008). "Bag-1 and Bcl-2 expression in breast tumors is associated with improved outcome and steroid receptor positivity." (PMID 18430249, 2008). "In this study, it was observed that NK cells can upregulate the expression of pro-apoptotic proteins such as C-Caspase 3 and BAX in breast tumor cells, while inhibiting the expression of anti-apoptotic proteins like BCL-2 and BCL-XL." (PMID 38891683, 2024). "For instance, BCL2 is an estrogen-regulated gene and is overexpressed in around 85% of ER-positive breast tumors." (PMID 36574653, 2023). "Further, gene expression of Bcl‐2, an antiapoptotic marker, was significantly decreased in breast tumors of emodin‐wounded mice compared to that of PBS (p = 0.0146)." (PMID 37821408, 2023). "Venetoclax is a selective BCL-2 inhibitor and is currently investigated for the treatment of patients with ER and BCL-2 positive breast tumors." (PMID 36574653, 2023). "Meanwhile, breast tumor with high PTPRT was associated with low proliferation rate (measured by Ki67) and high apoptotic rates (measured by BCL-2)." (PMID 34414233, 2021). "RANK signaling stimulates proliferation and survival of breast tumor cells through induction of cyclin D1 and Bcl-2 protein expression." (PMID 31796128, 2019). "It is possible that short-term treatment (0–48 h) with tamoxifen or AIs increases Bcl-2 and/or Bcl-xL levels, priming ERα+ breast tumor cells for Bcl-2/Bcl-xL inhibition, as was seen in ERα+ patient-derived xenograft models." (PMID 29343814, 2018). "Our current studies further revealed that drug-resistant TNBC cells have decreased expression of key regulators of resistance such as MDR1, MRP 1 and anti-apoptotic protein bcl-2 in drug-resistant xenograft breast tumors." (PMID 29158480, 2017). "In clinical studies, loss of p21 is associated with a TAM growth-inducing phenotype and increased Bcl-2 expression is an important phenomenon in metastatic TAM-resistant breast tumors." (PMID 28209156, 2017). "To examine if TLK2 overexpression upregulates BCL2 and ERα protein level in breast tumour tissues, we compared the BCL2 and ERα protein level in ER-positive breast cancers with or without TLK2 overexpression using the RPPA data available from TCGA." (PMID 27694828, 2016). "Recent studies of Bcl-2-specific inhibitors, in both in vitro models as well as in primary breast tumor xenografts that overexpress Bcl-2, have shown they potentiate apoptosis when combined with Tam." (PMID 25848915, 2015). "In several clinical studies, increased Bcl-2 expression in breast tumors has correlated with favorable response to endocrine therapy." (PMID 25848915, 2015). "Specifically, ABT-737 was recently observed to sensitize primary breast tumors overexpressing Bcl-2 to chemotherapy." (PMID 24236056, 2013). "In breast tumors, BCL2 expression measured prior to therapy correlates with ER expression and an improved response to antiestrogens." (PMID 20062536, 2010). "In conclusion, the results of our cell experiments indicated that the metabolites of probiotics CB‐AKK could induce apoptosis of 4T1 breast tumor cells by activating the Bcl‐2/Bax pathway." (PMID 40497373, 2025).
breast tumor (continued). "For example, aberrant STAT3 signaling promotes breast tumor progression through deregulation of the expression of downstream target genes, which control proliferation (Bcl-2, Bcl-xL, survivin, cyclin D1, c-Myc, and Mcl-1), angiogenesis (Hif1α and VEGF), and EMT (vimentin, Twist, MMP-9, and MMP-7)." (PMID 36446524, 2023). "Additionally, gene expression of anti‐apoptotic marker, Bcl‐2 also was significantly increased in breast tumors of surgical wounded mice compared to control (p < 0.05)." (PMID 36325601, 2022). "This study first revealed that Lut could potentiate the anticancer effects of Dox in breast tumor cells via the Bax/Bcl-2/Caspase-3 pathway." (PMID 34722681, 2021). "Using cell-derived and patient-derived xenograft models of HER2+/ER- breast tumors, our previous pre-clinical work provides evidence that dual targeting of BCL-2 and BCL-XL, via ABT-737 or ABT-263/navitoclax, enhanced the in vivo effectiveness of lapatinib or T-DM1." (PMID 33951110, 2021). "Although the number of apoptotic bodies in breast tumors is suggestive for the induction of apoptosis it is necessary to confirm apoptosis by other method, as is the expression of specific pro-apoptotic protein Bcl-2 in tumors." (PMID 28209156, 2017). "This suggests that TLK2 may play a role in modulating ERα protein level in breast tumours, whereas the BCL2 response may be an effect specific to TLK2 inhibition." (PMID 27694828, 2016). "Also, the combination was more effective in down-regulating the expression of NF-kB-regulated gene products (cyclin D1 and Bcl-2) in breast tumor tissues." (PMID 23284617, 2012). "In addition, the combination treatment induced an apoptotic effect evidenced by TUNEL staining and significantly decreased the expression of cyclin D1 and Bcl-2 in breast tumor tissues." (PMID 23284617, 2012). "Additionally, HER2 Delta 16 suppresses miR-15a/16 and deregulates BCL-2 to promote endocrine resistance in breast tumours, whereas PKC alpha downregulates miR-15a in head and neck squamous cell carcinoma." (PMID 21629246, 2011). "In contrast, other breast tumors appeared statistically enriched for three BCL2 specific probes." (PMID 21899728, 2011). "However, little information is available on the relationship between Bcl-2 and the rate of apoptotic and necrotic cell death in breast tumours." (PMID 9514059, 1998). "A statistically significant positive correlation of cytosolic BAG-1 immunostaining with Bcl-2 expression was found in 62 of 76 (82%) breast tumours coexpressing these proteins, suggesting that BAG-1 and Bcl-2 may be coregulated to some extent in early-stage invasive breast cancers." (PMID 28510570, 2017). "The question of whether Bcl-2 expression is associated with miR-21 production in HA-treated breast tumor cells has not been addressed." (PMID 24606718, 2014). "BAX, BCL2, NFKB1 and ABCG2 genes expression were compared by using breast tumor tissues on TCGA-BRCA." (PMID 41154846, 2025). "The aptamer–siRNA conjugate was internalized by HER2-positive tumor cells and silenced expressed levels of Bcl-2, improving the sensitivity of HER2-positive breast tumors to chemotherapy." (PMID 36430951, 2022). "The AS1411 aptamer, capable of binding the Bcl-2 mRNA-attaching protein nucleolin, was assessed for the capability to stimulate Bcl-2 gene cytotoxicity and instability in MDA-MB-231 and MCF-7 breast tumors." (PMID 36430951, 2022). "Bioinformatics analysis in our study indicates that the expression of PIK3CG, AKT, and BCL2 in TNBC tissues is significantly higher than that in adjacent healthy tissues and in hormone receptor-positive breast tumor tissues." (PMID 31680955, 2019).
breast tumor (continued). "The results demonstrated that TET-CSOSA/Cela significantly suppressed Bcl-2 activation of lung metastatic cells and reduced MMP-9 expression of 4T1 breast tumor cells by blocking NF-κB." (PMID 29355035, 2018). "In a study that recruited 11,212 women, Dawson and colleagues identified BCL2 as an independent indicator for all types of early-stage breast tumors, not just ER-positive tumors." (PMID 36853387, 2023). "Moreover, there is a positive relationship between GRP78 expression and the expression of the antiapoptotic protein Bcl-2, and down-regulating GRP78 promotes apoptosis in breast tumor cells." (PMID 34935899, 2022). "BCL2 amplification and copy number gains are uncommon in breast tumors, and there is no linear correlation between Bcl-2 gene transcripts and protein levels, thus pointing to post-transcriptional regulation of these proteins." (PMID 35053443, 2022). "Bcl-2, its anti-apoptotic relatives MCL-1 and BCL-XL, and the pro-apoptotic BH3-only ligand BIM were found to be coexpressed at relatively high levels in heterogeneous breast tumors." (PMID 26858789, 2016). "Both, Bcl-2 and Bcl-xL, exert effects on distant organ metastasis rather than on the primary breast tumor." (PMID 24098503, 2013). "In this, study, we aimed to evaluate the effect of SS on the expression of anti-apoptotic genes (Bcl-2 and BCL-XL), and also evaluate its effects on cell apoptosis and cell viability using MCF-7 cell line as well as evaluating its effect on tumor growth of spontaneous breast tumor (SMMT) in vivo." (PMID 35725497, 2022). "Additionally, a number of prosurvival (BCL2, PPEF2) and proapoptosis (BID, HEBP2, and PKNOX1) genes were up- and downregulated, respectively, in bone metastases compared with primary breast tumors." (PMID 23174366, 2012). "There was a trend for an effect of adjuvant chemotherapy on disease-free survival both for patients with Bcl-2-positive (HR-0.61, 95% CI 0.35-1.06, P = 0.07) and negative (HR = 0.55, 95% CI 0.27-1.12, P = 0.09) breast tumours at a median follow-up of 49 months." (PMID 8679463, 1996). "Using copy-number and sequencing data of a large cohort of 171 breast tumours (38 metastasized, 130 no-metastasis) we observed an increased frequency of losses in those tumours that metastasized for many of the top ranked genes including BCL2 (18% vs 13%), IGFBP7 (11% vs 6%), IGF1 (8% vs 2%)." (PMID 20673354, 2010). "In ER+ primary breast tumor xenografts venetoclax (ABT-199) showed similar activity to ABT-737, indicating the higher requirement for Bcl-2 rather than Bcl-xL downregulation for its activity." (PMID 35053443, 2022). "In an independent series of breast tumor samples (19 nonrelapsing and 14 relapsing), reduced expression of ESR1/ERα, IGFBP4, SNCG, BCL2, and FOS was observed in the relapsing group and was associated with a shorter overall survival." (PMID 18928543, 2008).